AXL (AXL receptor tyrosine kinase)
Diseases named in the same sentence as AXL in open-access papers (continued):
Sharing a sentence is not in itself a finding about the gene and the disease.
non-small cell lung carcinoma (60 papers, 2012 to 2025). A group of at least three distinct histological types of lung cancer, including non-small cell squamous cell carcinoma, adenocarcinoma, and large cell carcinoma. "One such RTK, tyrosine-protein kinase receptor UFO (AXL), has been implicated for its role in resistance to imatinib and erlotinib in leukemia and non-small cell lung cancer, respectively." (PMID 33672595, 2021). "Although amplification and mutations are rare in AXL, overexpression of the AXL protein has been reported in many different cancers, including breast, ovarian, prostate, non-small cell lung cancer and head and neck squamous cell carcinoma." (PMID 34439388, 2021). "Similar discrepancies regarding associations of AXL expression with clinico-pathological parameters and survival were also found in other tumor entities such as non-small cell lung cancer." (PMID 28025482, 2016). "The receptor tyrosine kinase AXL has been implicated in several tumor entities and a selective AXL small molecule inhibitor (BGB324) is currently being tested in clinical trials for patients suffering from non-small cell lung cancer or acute myeloid leukemia." (PMID 28025482, 2016). "Studies have indicated that AXL expression is significantly upregulated in EGFR-mutant non-small cell lung cancer cells that have developed resistance and that its degradation rate is inhibited." (PMID 40304000, 2025). "For instance, the combination of microwave ablation and AXL-CAR T cells has demonstrated superior anti-tumor efficacy in AXL-positive non-small cell lung cancer patient-derived xenograft tumors, achieved through TME remodeling." (PMID 38796455, 2024). "Recently, in non-small cell lung cancer cells, the AXL inhibitor BGB324 (Bencentinib) has been shown to induce DNA damage and replication stress indicated by ATR/CHK1 phosphorylation." (PMID 35955805, 2022). "This information suggests that AXL cleavage plays a role in the cancer drug resistance of non-small-cell lung cancer cells." (PMID 33947097, 2021). "AXL has been reported to contribute to cancer metastasis, suppression of immune response, and drug resistance in various cancers such as non-small cell lung cancer (NSCLC) and triple-negative breast cancer (TNBC)." (PMID 34721022, 2021). "The non-small cell lung cancer cell line H1299 has been shown to exhibit markedly increased AXL protein expression." (PMID 33425754, 2020). "R428 (bemcentinib, BGB324), a selective small-molecule inhibitor of AXL, is currently being evaluated in phase II trials for the treatment of non-small-cell lung cancer (NSCLC) and acute myelocytic leukemia (AML)." (PMID 31781483, 2019). "Through the global gene expression analysis and the functional annotation clustering, we found that AXL expression positively correlated with mRNA expressions of immune checkpoint molecules and chemokine receptors in non-small-cell lung cancers." (PMID 30744655, 2019). "Several small molecule inhibitors are being developed, but, currently, BGB324 (R248) is the only selective AXL inhibitor that is used in phase I clinical trials for patients suffering from non-small cell lung cancer or acute myeloid leukemia." (PMID 28025482, 2016). "AXL belongs to a tyrosine kinase family, and its inhibition promotes apoptosis, blocks growth and enhances chemosensitivity in human non-small cell lung cancer." (PMID 26646320, 2016). "BGB324 (formerly known as R428) is a first-in-class, highly selective small-molecule AXL inhibitor that is currently in Phase I clinical trials to assess its clinical responses in patients with acute myeloid lymphoma and non-small cell lung cancer (NSCLC)." (PMID 27829217, 2016). "Studies in non-small cell lung cancer identified cross-talk between AXL and epidermal growth factor receptor, suggesting the possibility of a similar interaction between FGFR3 and AXL in CLL." (PMID 27834816, 2016).
non-small cell lung carcinoma (continued). "Their findings suggest that tumor guided radiation enhances the activation, infiltration, persistence, and tumor-suppressive properties of AXL-CAR-T cells in non-small cell lung cancer patient-derived xenograft tumors via tumor microenvironment (TME) remodeling." (PMID 39759518, 2024). "AXL-driven AKT activation is associated with increased tumor aggressiveness and poor prognosis in various cancers, including hepatocellular carcinoma and non-small cell lung cancer." (PMID 39597836, 2024). "Furthermore, AXL expression was sufficient to mediate acquired resistance to cetuximab in models of non-small cell lung cancer (NSCLC) and head and neck squamous cell carcinoma (HNSCC)." (PMID 31694201, 2019). "Thus, AXL activation-induced cell softening promotes malignant progression in non-small cell lung cancer and represents a key biophysical property of cancer cells." (PMID 29259259, 2017). "Additionally, R428 (BGB324), a small molecule inhibitor of AXL, used in our in vitro experiments, is currently in clinical trials in acute myeloid leukemia and in non-small cell lung cancer." (PMID 27764792, 2016). "AB-329 (formerly DS-1205b), a selective small-molecule AXL inhibitor, has demonstrated safety and preliminary efficacy in combination with EGFR inhibitors in clinical trials for non-small cell lung cancer (NSCLC)." (PMID 41009462, 2025). "Together, this study suggests that AXL/SFK/AKT and CDCP1/SFK/AKT signaling pathways play some roles in acquired osimertinib resistance of non-small cell lung cancer." (PMID 35643725, 2022). "As demonstrated in non-small cell lung cancer (NSCLC) cells, AXL is part of a group of genes controlled by methylation of cytosine nucleotides in their promoter region rich in GC repeats." (PMID 35572601, 2022). "Enapotamab Vedotin or HuMax-AXL-ADC is another anti-AXL ADC, firstly tested in vitro and in vivo in preclinical models of non-small cell lung cancer." (PMID 34440182, 2021). "For instance, one study showed that γ-secretase-uncleavable AXL mutant enhanced chemoresistance to erlotinib, an EGFR inhibitor, in non-small-cell lung cancer cells." (PMID 33947097, 2021). "MERTK and AXL are members of the TAM family of receptor tyrosine kinases and are abnormally expressed in 69% and 93% of non-small cell lung cancers (NSCLCs), respectively." (PMID 34830794, 2021). "Non-small cell lung cancer (NSCLC), a prevalent and devastating disease, shows overexpression and activation of MER and AXL." (PMID 34778071, 2021). "For example, AXL regulation of miR-374a and miR-548b conferred drug resistance to EGFR inhibitors such as gefitinib in non-small cell lung cancer (NSCLC), and activated AXL is a prognostic marker and potential therapeutic target in NSCLC." (PMID 32992696, 2020). "AXL is a promising novel therapeutic target in a variety of cancers, such as BC, acute myeloid leukemia (AML), non-small cell lung cancer (NSCLC), pancreatic cancer and prostate cancer." (PMID 25528764, 2014). "Interestingly, in human non-small cell lung cancer cells (HCC827), α-secretase (ADAM10) can cleave the full-length AXL (AXL-FL) and release the extracellular domain into the blood termed soluble Axl (sAxl)." (PMID 33954117, 2021). "In studies on non-small cell lung cancer (NSCLC) cells resistant to epidermal growth factor receptor tyrosine kinase inhibitor (EGFR-TKI), NPS-1034 effectively overcame drug resistance and reduced the viabilities of drug-resistant cells in vitro via AXL or MET inhibition." (PMID 39000029, 2024). "Here, we show that AXL, which is highly expressed in non-small cell lung cancer (NSCLC) but not in normal tissues, might be a target for CAR T cell therapy." (PMID 36261437, 2022). "In several non-small cell lung cancer (NSCLC), breast cancer (BRC) and colorectal cancer cell lines, miR-199a had a pivotal role in tumorigenesis affecting activities such as tumor growth, migration, invasion and in vivo distant metastasis by directly targeting AXL." (PMID 22942713, 2012).
glioblastoma (48 papers, 2012 to 2025). The most malignant astrocytic tumor (WHO grade IV). "Investigating the therapeutic potential for pharmacologic targeting of S6K1 in PTEN-deficient glioblastoma, we previously found that co-targeting AXL with S6K1 induced cytotoxic responses selectively in PTEN-deficient glioblastoma cells." (PMID 39087397, 2024). "Since glioblastoma is strongly associated with the immune system, AXL expression is favorably connected with large concentrations of immune system indicators such as monocytes and dendritic cells." (PMID 38391974, 2024). "The upregulation of AXL signaling is usually associated with glioblastoma development and progression." (PMID 38391974, 2024). "Here, we establish a definitive requirement of AXL for infection of human glioblastoma cells by both Zika and Spondweni virus." (PMID 40062839, 2025). "In agreement with our study, researchers have previously found that AXL is overexpressed in glioblastoma cells and have shown that its inhibition induces apoptosis in vivo and suppresses cell migration and invasion." (PMID 40725039, 2025). "AXL can also alter other receptor signalling; for example, EGF can activate pro-invasive genes via activation of EGFR-AXL heterodimer in glioblastoma cells." (PMID 41511287, 2025). "RTKs including EGFR, VEGFR, PDGFR, MET, and AXL regulate essential activities such as cell proliferation, survival, invasion, and angiogenesis, enhancing glioblastoma’s resistance to standard treatments." (PMID 40332008, 2025). "The two TAM receptors that are predominant in glioblastoma-associated macrophages are MERTK and AXL." (PMID 40610434, 2025). "It is assumed that a domino effect occurs wherein glioblastoma cells express more AXL when they come into contact with the extracellular fluid of nearby cells irradiated by radiotherapy." (PMID 38391974, 2024). "Based on these premises, in this review we mainly focused on the role of AXL in the course of glioblastoma, considering its primary biological mechanisms and as a possible target for the application of the most recent treatments." (PMID 38391974, 2024). "Simultaneously, the combined impact of conventional therapy for glioblastoma and AXL-specific tyrosine kinase inhibitor (TKI) R428 (also known as Bemcentinib) was investigated." (PMID 38391974, 2024). "It has been demonstrated that AXL and/or GAS6 overexpression were associated with a worse prognosis and more aggressive malignancy, as seen, for instance, in glioblastoma patients." (PMID 38391974, 2024). "CAR-KHYG-1 cells have been able to selectively eliminate glioblastoma cells, thus demonstrating that AXL, c-Met and FORL1 can be very valuable therapeutic targets to counteract glioblastoma." (PMID 38391974, 2024). "Liu and colleagues investigated the effects of intracranial administration of (Z)-n-butylidenephthalide [(Z)-BP], released via Cerebraca Wafers (CWs), in combination with TMZ to target AXL and mTOR in the glioblastoma framework." (PMID 38391974, 2024). "Thus, considering the influence of AXL on iNOS/NO expression and the biological implications for tumor environment caused by this crosstalk, more evidence of the link between AXL and the pro-inflammatory role of iNOS will certainly emerge in the future, especially in glioblastoma." (PMID 38391974, 2024). "In the general understanding of glioblastoma, it becomes imperative to figure out more suitable therapeutic approaches, and in this pathological context, the interactions with AXL are becoming widely more studied." (PMID 38391974, 2024). "By circumventing redundancy in signaling between S6K1/2 and AXL, combination LY-2584702 and BMS-777607 treatment presents a novel kinase-directed approach to capitalize on the vulnerability of PTEN-deficient glioblastomas to inhibit pyrimidine biosynthesis." (PMID 39087397, 2024).
glioblastoma (continued). "CAR KHYG-1 NK cells that can target c-Met also known as hepatocyte growth factor receptor (HGFR) and AXL proteins that are overexpressed in glioblastoma cell lines, led to cytokine secretion and glioblastoma cell lysis." (PMID 36792722, 2023). "A Phase I clinical trial using this AXL inhibitor is currently being tested in glioblastoma which progressed after radiation and other combined treatments (NCT03965494)." (PMID 35955805, 2022). "A tyrosine kinase AXL inhibitor R428 (BGB324) was found to reverse radiation resistance in glioblastoma cell lines." (PMID 35955805, 2022). "In syngeneic murine glioblastoma models, targeting AXL plus PD-1 effectively prolonged the survival of glioblastoma-bearing mice." (PMID 35572601, 2022). "Recently, GAS6/AXL-triggered actin remodeling has been demonstrated to play an important role in driving the invasion and macropinocytosis of glioblastoma cells in a PI3K-dependent manner." (PMID 34831142, 2021). "REV-ERBβ expression promoted proliferation, migration, and invasion of glioblastoma multiforme (GBM) through transcriptional upregulation of AXL receptor tyrosine kinase (AXL), an EMT key regulator." (PMID 32195174, 2020). "The membrane protein AXL is predominantly involved in the infection of various cell types including glioblastoma, epithelial, microglial and human Sertoli cells." (PMID 30081445, 2018). "Michael Platten’s lab identified that AXL, a novel target gene in glioblastoma, is positively regulated by EZH2 and mediates invasiveness driven by EZH2." (PMID 29642503, 2018). "In glioblastoma stem-like cells AXL inhibition reduced the self-renewal capacity in vitro and inhibited the growth of patient derived xenografts in vivo." (PMID 27834845, 2016). "In addition, overexpression of AXL has been implicated in the development and progression of numerous malignancies; furthermore, AXL has been identified as a predictor of poor patient outcome in lung, breast, and pancreatic cancer, renal cell carcinoma, and glioblastoma." (PMID 26573603, 2015). "Furthermore, we identified for the first time the binding interaction between FOXM1, AXL, and eEF2K within the glioblastoma concept." (PMID 40725039, 2025). "Understanding and better evaluating AXL could lead to the realization of drugs or chemical agents capable of counteracting glioblastoma progression." (PMID 38391974, 2024). "They discovered that the mesenchymal (MES) glioblastoma subtype had increased expression of AXL." (PMID 38391974, 2024). "Recently, quercetin was reported to induce apoptosis by inhibiting AXL in glioblastoma cells." (PMID 34572484, 2021). "Notably, AXL is demonstrated as a key regulator for mesenchymal GSC, and knockdown of AXL significantly diminishes the in vitro self-renewal of mesenchymal GSCs and suppresses the in vivo growth of glioblastoma in xenograft mice." (PMID 34831142, 2021). "Indeed, while BMS-777607 is marketed as a c-MET inhibitor, one recent study utilized it to therapeutically target AXL in a model of glioblastoma." (PMID 30863365, 2019). "Thus, expression of AXL during glioblastoma remains a key step for in-depth study." (PMID 38391974, 2024). "And for PROS, it was secreted by tumor-associated macrophages and targeted AXL on glioma stem cells, while we discovered that the high-GS also functioned as the sender to interact with M2 macrophages, suggesting the PROS-AXL-mediated mutual interplay between macrophage and glioblastoma cells." (PMID 36494582, 2023). "Given this, AXL is a promising therapeutic target, and R428 (bemcentinib), a first-in-class AXL kinase inhibitor, is currently being evaluated in phase 2 clinical trials for metastatic lung and triple-negative breast cancer, glioblastoma, and acute myeloid leukemia." (PMID 35622156, 2022).
glioblastoma (continued). "An in vitro study of four glioblastoma cell lines revealed that CA’s anti-metastatic mechanism is a result of AXL pathway down-regulation and, more precisely, CA stimulates the polyubiquitination/proteasomal degradation of AXL and subsequently inhibits the JAK2/MEK/ERK axis." (PMID 36012159, 2022). "In addition, AXL also plays an important role in regulation of glioblastoma stem-like cells." (PMID 34831142, 2021). "It has been shown that malignant human gliomas often overexpress AXL and/or GAS6, and that individuals with glioblastoma who have elevated levels of these proteins have a markedly shortened time to tumor growth." (PMID 38391974, 2024). "Bielecka and colleagues tested selective AXL/TAM inhibitors (Bemcentinib, Gilteritinib and LDC1267) in glioblastoma cells." (PMID 38391974, 2024). "Corosolic acid 20 μM notably reduced AXL and GAS6 expression in glioblastoma cell lines, also lowering the phosphorylated expression of JAK2, MEK and ERK." (PMID 38391974, 2024). "By phosphorylating AXL and activating downstream NF-κB signal pathway, PROS1 promotes Glioblastoma (GBM) tumor growth." (PMID 37328828, 2023). "We incubated serum-starved glioblastoma LN229 cells, which we previously used for the identification of AXL interactome, with purified Myc-tagged version of GAS6 (hereafter called GAS6) for various time periods." (PMID 35622156, 2022). "The treatment of glioblastoma cells with Hepatocyte Growth Factor (HGF) resulted in cMET-AXL co-clustering, AXL phosphorylation at Y779, recruitment of ELMO-DOCK180 complex, RAC1 activation, reorganization of the cytoskeleton, and enhanced cell motility." (PMID 34638349, 2021). "It has been reported that knockdown of AXL expression by clustered regularly interspaced short palindromic repeats (CRISPR) interference in HeLa cells and U87 glioblastoma cells prevented the infection by ZIKV." (PMID 30081445, 2018). "The small molecule n-Butylidenephthalide (BP) reduced expression of AXL and stemness-related genes, including CD133, Sox2 and Oct4, in a dose-dependent manner in glioblastoma." (PMID 29642503, 2018). "Indeed, genetic and therapeutic inhibition of AXL is sufficient to decrease tumor growth in some tumor types including squamous cell carcinomas, Kaposi sarcomas, pancreatic adenocarcinomas, mesotheliomas, schwannomas, ocular melanomas, B-cell chronic lymphocytic leukemia, and glioblastomas." (PMID 27834845, 2016). "We and others previously demonstrated co-expression of MERTK and AXL, MERTK and GAS6 (a TAM kinase ligand), and AXL and GAS6 in tumor biopsies from pediatric patients with glioblastoma multiforme." (PMID 27783662, 2016). "A novel multikinase inhibitor of MET, VERFR1, AXL, TIE2, KIT, FLT3, and RET, called cabozantinib (also known as XL184), inhibits the growth, metastasis, and angiogenesis in pancreatic cancer and glioblastoma, and reduces resistance to gemcitabine." (PMID 26225770, 2015). "In mesothelioma AXL-mediated invasiveness involves the PI3K/AKT/mTOR pathway, a pathway that is currently targeted in glioblastoma early drug development." (PMID 23077658, 2012). "In glioblastoma CSCs, NR1D2 regulates proliferation through the AXL/PI3/Akt signalling pathways." (PMID 40564218, 2025). "Interestingly, infection of AXL KO cells by SPONV was also suppressed, suggesting that infection of these glioblastoma cells by SPONV also requires AXL." (PMID 40062839, 2025). "In that study, AXL was identified as a new transcriptional target of NR1D2: the regulatory effect of NR1D2 on the PI3K/AKT axis promotes the proliferation, migration, and invasion of glioblastoma cells." (PMID 39273313, 2024). "The obtained results show that AXL and c-Met were overexpressed in most glioblastoma cell lines tested (11 out of 13), but not in neuroblastoma cells (0 out of 8)." (PMID 38391974, 2024). "Epigenetic modifiers, including EZH2, sustain AXL expression in glioblastoma cells in a manner that seems independent of histone or DNA methylation." (PMID 35572601, 2022).